RNA5S5 (RNA, 5S ribosomal 5)
Synonyms: RN5S5
Gene: Ribosomal RNA gene on chromosome 1 (228,619,232 to 228,619,350, reverse strand). Ensembl gene ENSG00000199396.
Gene Ontology:
Molecular function: structural constituent of ribosome
Cellular component: ribosome
Homologues: Paralogues in human: RNA5S1 (100% identical), RNA5S10 (100% identical), RNA5S11 (100% identical), RNA5S12 (100% identical), RNA5S13 (100% identical), RNA5S14 (100% identical), RNA5S15 (100% identical), RNA5S16 (100% identical), RNA5S17 (100% identical), RNA5S2 (100% identical), RNA5S3 (100% identical), RNA5S4 (100% identical), and 26 more.